SIRT1 (sirtuin 1)
Diseases named in the same sentence as SIRT1 in open-access papers (continued):
Sharing a sentence is not in itself a finding about the gene and the disease.
depression (continued). "Intriguingly, SIRT1 inhibitor countervailed the inhibitory effect of AG on NLRP3 inflammasome, which indicated that targeting the SIRT1-mediated NLRP3 inflammasome axis might be a possible mechanism of AG to treat depression." (PMID 37920216, 2023). "On the other side, anxiety- and depression-like behaviour may be ameliorated by antioxidants via up-regulation of the sirtuin 1 (SIRT1)–nuclear factor erythroid 2-related factor 2 (Nrf2)–haeme oxygenase 1 (HO-1)–glutathione peroxidase 4 (Gpx4) axis." (PMID 37240914, 2023). "The beneficial effect of luteolin through Sirt1/NF-κB/NLRP3 signaling pathway might be a therapeutic strategy for the depression-related dry eye disorder." (PMID 36641776, 2023). "Additionally, inhibition of hippocampal Sirt1 function in mice on the basis of genetics and pharmacology can lead to the increase of depression-like behaviors." (PMID 36641776, 2023). "Finally, being related to physical activity, SIRT1 is involved in the development of addictions, anxiety, and depression: all clinical aspects reported by patients affected by AN." (PMID 37373917, 2023). "Based on the discussion and analysis of the mechanism of SIRT1 in the occurrence of depression and the improvement of depression by exercise, this article innovatively and systematically demonstrates the specific regulatory mechanism of SIRT1 in the improvement of depression by exercise." (PMID 37239191, 2023). "SIRT1, a class-III HDAC, has been found to be involved in chronic pain-associated depression." (PMID 35959106, 2022). "The results showed that SIRT1 was a mediator of S-ketamine in alleviating depression-like behavior." (PMID 35664490, 2022). "Of three distinct susceptible variants (an exonic variant, rs2273773, and two novel intronic variants) that were identified in and near SIRT1, none showed a significant association with depression." (PMID 35370858, 2022). "In summary, our results demonstrate that lncRNA-84277/miR-128-3p/SIRT1 axis may act as a new ceRNA regulatory network, participating in the development of chronic pain-related depression." (PMID 35959106, 2022). "SIRT1 is a mediator of S-ketamine in alleviating depression-like behavior." (PMID 35664490, 2022). "Meanwhile, SIRT1 inhibitor reversed the effect of S-ketamine in relieving depression-like behavior." (PMID 35664490, 2022). "Interestingly, we found that by blocking the expressions of Sirt1 and AMPK, the therapeutic efficacy of PAP was altered, suggesting that AMPK and Sirt1 play critical roles in the PAP-relieved depression." (PMID 35401226, 2022). "The data indicated that Sirt1 played a critical role in the regulation of PAP-treated depression." (PMID 35401226, 2022). "Taken together, we hypothesized that SIRT1 was a mediator of S-ketamine in increasing the BDNF level, and S-ketamine alleviated depression symptoms through the SIRT1-dependent BDNF pathway." (PMID 35664490, 2022). "Moreover, the Sirt1 activity in dentate gyrus (DG) of Hip was decreased when chronic stress exposure and genetic or pharmacologic ablation of Hip Sirt1 can lead to depression." (PMID 35130906, 2022). "Furthermore, a mouse study suggested that hippocampal SIRT1 signaling can mediate depression-like behaviors, and a clinical trial also observed significantly reduced peripheral blood SIRT1 mRNA in depressive patients compared with healthy controls." (PMID 35370858, 2022). "Furthermore, it was revealed that hippocampal SIRT1 activity increases in response to chronic variable stress, a rodent model of depression." (PMID 35936890, 2022). "Therefore, we uncovered a new mechanism by which lncRNA-84277 functions as a ceRNA and weakens the endogenous inhibitory effect of miR-128-3p on SIRT1 in the development of chronic pain-related depression." (PMID 35959106, 2022). "For instance, NAD is able to suppress depression by increasing SIRT1 activity." (PMID 36552159, 2022).
depression (continued). "Sirtuin type 1 inhibitor EX-527 was used to downregulate the SIRT1 expression to further evaluate whether SIRT1 was a mediator of S-ketamine in alleviating depression-like behavior." (PMID 35664490, 2022). "However, the upstream mechanisms for SIRT1 to regulate chronic pain-related depression is still unclear." (PMID 35959106, 2022). "A study conducted on stressed mice indicated that resveratrol intraperitoneal (i.p.)treatment can prevent anxiety and depression via SIRT1 activation and downstream extracellular signal-regulated kinases (ERK1/2), which have been reported as participating in a pro-depressive mechanism." (PMID 33669121, 2021). "Furthermore, polymorphisms or genetic variation in SIRT1 and SIRT2 in the normal and depression populations have also been studied to investigate the genetic association of SIRT1 and SIRT2 and the susceptibility, onset and course of depression." (PMID 33669121, 2021). "There is a growing body of evidence that SIRT1 and SIRT2 may have a role in depression, linked to inflammation." (PMID 33669121, 2021). "An animal study suggested that SIRT1 contributes to the development of depression." (PMID 34276306, 2021). "Besides, a case-control study of SIRT1 SNPs and major depressive disorder patients (455 MDD patients and 766 controls) in the Japanese population also suggested a significant association between SIRT1 rs10997875 polymorphism and depression." (PMID 33669121, 2021). "SIRT1 has been accepted as a target gene of miR-155 that alleviates major depressive disorder." (PMID 34893074, 2021). "Although the sex-dependent role of SIRT1 in depression is still unclear, taken together with the results of clinical studies, these observations suggest that SIRT1 may be associated with the etiopathogenesis of sex-related differences in depression." (PMID 34276306, 2021). "Although very limited data can be obtained from existing clinical trials of SIRT modulators in depression, some evidence supporting the anti-inflammatory effects of the SIRT1 activators can be found in clinical trials of other inflammation-associated conditions." (PMID 33669121, 2021). "In addition to miR-132 and miR-134, CUMS gives rise to depression-like behaviours via SIRT1/miR-124, and swimming exercise can reverse the expression of SIRT1 protein and the expression of these miRNAs in CUMS mice." (PMID 34947970, 2021). "Importantly, many ginsenosides can be used to prevent and treat oxidative stress, inflammation, aging, tumorigenesis, depression, and other conditions by targeting the SIRT1 signaling pathway." (PMID 34188208, 2021). "Furthermore, these results were reproduced in animal studies; altered activity of SIRT1 in the hippocampus and the NAc provoked depressive-like behaviors in animal models of depression." (PMID 34065586, 2021). "Based upon our results, we postulate that loss or reduction of SIRT1 activity may contribute to hypofunction of the PFC, leading to the development of depression in males." (PMID 30705425, 2020). "In this model of depression, we found that SIRT1 activity was increased." (PMID 33228716, 2020). "Rs3758391 is a functional locus of Sirtuin (SIRT1) involving depression etiology." (PMID 32849821, 2020). "Other investigations by targeting SIRT1 in particular brain regions suggest that the effects of SIRT1 activity on depression-like behaviors may be brain-region dependent." (PMID 30705425, 2020). "In line with the functional difference between prelimbic and infralimbic mPFC, our data suggest abnormal SIRT1 activity and impaired neuronal excitability in prelimbic pyramidal neurons may contribute to the development of depression." (PMID 30705425, 2020). "Because SIRT1 activity was enhanced in the restraint depressive mice, we initially hypothesized that NAM could mediate depression by reducing SIRT1 activity." (PMID 33228716, 2020).
depression (continued). "Since a number of other miRNAs, such miR-9, miR-146, miR-143, miR-132, miR-34a, miR-22, and miR-217, have also been shown to target SIRT1 in other diseases, it is worth investigating whether these miRNAs could serve as therapeutic targets in depression." (PMID 31431514, 2019). "Therefore, SIRT1 is frequently pursued as a target for treatment of depression, whereby miRNAs, which are broad-spectrum regulators of genes, have been shown to regulate SIRT1 expression." (PMID 31431514, 2019). "MiR-124 overexpression exacerbated depression-like behaviors and decreased SIRT1." (PMID 31431514, 2019). "Next, the effects of SIRT1 overexpression on CUMS-induced depression-like behavior were evaluated." (PMID 31431514, 2019). "When Sirt1 was activated, development of depression-related phenotypes and abnormal dendritic structures induced by chronic stress could be blocked." (PMID 29643977, 2018). "This opposite role of Sirt1 and Sirt2 is thought to be age-dependent, and the balance of these two Sirts might be crucial in part for the regulation of depression by Sirt1." (PMID 29643977, 2018). "The Sirt1 inhibitor sirtinol could restore histone acetylation, then improve the behavior of depression." (PMID 29643977, 2018). "This review describes the different effects of Sirt1 on depression and possible mechanisms and points to the direction that Sirt1 could serve as a novel therapeutic target for clinical treatment of depression." (PMID 29643977, 2018). "The dysregulated SIRT1 signaling plays an important role in depression-like behaviors." (PMID 30482883, 2018). "SIRT1 induction in the NAc promoted depression- and anxiety-like behaviors." (PMID 30416425, 2018). "Two previous studies demonstrated a relationship between DD and SIRT1 rs12415800 allele frequencies in Han Chinese melancholic DD women and – to a much smaller degree – in an European self-reporting depression sample coded as rs187810158 in that study." (PMID 30662452, 2018). "For example, it was demonstrated that mice with brain-specific Sirt1 knockout decreased anxiety and developed resilience to depression induced by social defeat, while mice with global Sirt1 overexpression had elevated anxiety and increased susceptibility to depression." (PMID 29643977, 2018). "It was also found that there is a link between the Sirt1 gene (rs3758391) and depressive disorders." (PMID 29643977, 2018). "Furthermore, taken together with the human genetic studies, these studies define an important relationship between SIRT1-dependent mechanisms and development of anxiety and depressive disorder-related behaviors." (PMID 30271963, 2018). "However, the involvement of SIRT1 in anxiety and depressive disorder-related behavior regulation was previously studied under chronic SIRT1 activity modulation such as SIRT1 knockout, overexpression or long-term pharmacological modulation." (PMID 30271963, 2018). "Therefore, we need to further investigate how brain SIRT1 contributes to the manifestation of depression and how it correlates with the peripheral SIRT1 levels to assess the clinical utility of SIRT1 as a biological marker for depression." (PMID 29163009, 2017). "Interestingly, a current study suggested that the expression of SIRT1, 2 and 6 mRNA in blood cells was altered in patients with mood disorders such as depression." (PMID 27065808, 2016). "Aberrant expression and/or function of Sirt1 may contribute to the pathophysiology of depression via neuroinflammation and dysregulation of neurogenesis." (PMID 27517628, 2016). "We first determined whether SIRT1 was a marker of depression; as per this hypothesis, patients had significantly lower SIRT1 levels than control subjects (clinical state: t =2.15, P=0.037)." (PMID 26327687, 2015).
depression (continued). "To determine the contribution of SIRT1 to the development of depression, we pharmacologically activated or inhibited SIRT1 function with resveratrol and selisistat (EX-527), respectively, during juvenile age and measured the effects on depression-related behavior in adulthood." (PMID 26327687, 2015). "Notably, using a pharmacological strategy, we demonstrated a critical function of SIRT1 during postnatal development in the long-term regulation of depression-like behavior." (PMID 26327687, 2015). "Further, SIRT1 variants have been associated with depressive disorder, but not with bipolar disorder." (PMID 26509718, 2015). "In addition, our study gave further support for the role of SIRT1 in depressive disorders (rs3758391) and diastolic blood pressure (rs2273773)." (PMID 26509718, 2015). "UB efficiently alleviated depression‐related behaviors, accompanied by suppressed microglia activation, neuroinflammation, changes of classic activation (M1)/alternative activation (M2) polarization and recovered sirtuin‐1 (SIRT1) and forkhead box protein O1 (FOXO1) expression in the hippocampus." (PMID 40237232, 2025). "SIRT1 is an unordered protein due to a flexible loop involved in the active C-site residues, forming about half of the total sequence, and is predominantly known for its role in longevity and lifespan, though this has been recently expanded into anxiety and depression." (PMID 39404407, 2024). "However, how SIRT1 acts during exercise and then improves depression is yet to be explored." (PMID 37239191, 2023). "The results showed that maternal separation led to increased anxiety- and depression-like behaviors, enhanced the levels of pro-inflammatory cytokines, and downregulated the Sirt1/NF-κB signaling pathway in the male offspring; however, these effects could be reversed by treatment with resveratrol." (PMID 37273278, 2023). "In addition, the selective inhibition of Sirt1 could weaken the therapeutic effect of luteolin on depression-related dry eye disorder." (PMID 36641776, 2023). "Sirt1 has a neuroprotective effect in neurodegenerative diseases and can regulate downstream transcription factors such as nuclear factor erythroid 2-related factor 2 (Nrf2) and NF-κB to prevent inflammation damage, which is an important factor in the pathogenesis of depression." (PMID 37124257, 2023). "Moreover, SIRT1 was a mediator of S-ketamine in alleviating depression-like behavior." (PMID 35664490, 2022). "However, how SIRT1 affects the brain structure of human depression is still unknown, and there are few related studies." (PMID 36177213, 2022). "In addition, AMPK and Sirt1 played critical roles in the PAP-relieved depression." (PMID 35401226, 2022). "However, whether lncRNAs are involved in SIRT1-mediated chronic pain-related depression remains largely unknown." (PMID 35959106, 2022). "This role may resolve some of the controversies surrounding the change of SIRT1 in depression." (PMID 33228716, 2020). "We hypothesized that the mPFC mediates SIRT1 action on depression-like behaviors." (PMID 30705425, 2020). "The important role of SIRT1 gene in depression has been demonstrated, which leads to the hypothesis that clinical treatment of depression can be carried out by using the therapeutic drugs that directly target SIRT1." (PMID 31431514, 2019). "It has been reported that Sirt1 is mostly believed to be neuroprotective while Sirt2 may enhance or facilitate neurodegeneration in stress-related psychiatric disorders including depression." (PMID 29643977, 2018). "MSC therapy reduces oxidative stress, a key feature of major depressive disorder (MDD), by generating antioxidants such as hydrogen sulfide (H2S), which upregulates Sirt1 and modulates inflammatory cytokines." (PMID 40943227, 2025). "Exercise can significantly improve depression, and its mechanism is closely related to the enhancement of mitochondrial biogenesis through the AMPK, PGC-1α, and SIRT1 signaling pathways." (PMID 40699781, 2025).
depression (continued). "In a word, this study indicates that PF can effectively alleviate the depression-like behavior of CUMS mice, which depends on the SIRT1 signal to regulate the activation of NLRP3 inflammasome and pyroptosis." (PMID 39684254, 2024). "Previous studies indicate that pharmacological activation or local overexpression of SIRT1 in the hippocampus or BNST can reverse chronic stress-induced anxiety- and depression-like behaviors." (PMID 39744519, 2024). "Specifically, E2 can activate the ERα/sirtuin 1 (SIRT1)/NF-κB signaling pathway, leading to an improvement in depression-like behavior." (PMID 38309292, 2024). "In total, hippocampal SIRT1 regulates the SIRT1/PGC-1α/NRF1/TFAM/mitochondria biogenesis axis to mediate the ameliorative effect of treadmill exercise on anxiety- and depression-like behaviors in APP/PS1 mice." (PMID 39744519, 2024). "Therefore, SIRT1 signaling may mediate anxiety- and depression-like behaviors in AD model mice." (PMID 39744519, 2024). "We further examined the expression of SirT1 and GABA in primary cortical neurons, which are involved in mood disorders like depression and anxiety." (PMID 38473763, 2024). "The use of S-Ketamine, an FDA-approved medication for treatment-resistant depression, in rodents following chronic unpredictable stress produces increased brain-derived neurotrophic factor (BDNF) and SIRT1." (PMID 39404407, 2024). "A previous study showed that resveratrol activated sirtuin-1 in OVX mice, reducing anxiety and depression-like behaviors by inhibiting the hippocampus’s NF-κB and NLRP3 signaling pathways, thereby preventing neuroinflammatory processes." (PMID 38306547, 2024). "Here, we demonstrate that treadmill exercise improved anxiety- and depression-like behaviors in 6-month-old APP/PS1 mice, while also increasing hippocampal SIRT1 levels." (PMID 39744519, 2024). "We first observed that treadmill exercise improved anxiety- and depression-like behaviors in six-month-old APP/PS1 mice and increased SIRT1 levels in the hippocampus." (PMID 39744519, 2024). "It is presumed that SIRT1 can inhibit the expression of IL-6 in the CA1 region of the hippocampus, thereby inducing depression." (PMID 37239191, 2023). "Our results displayed that Sirt1 was involved in the alterations of pyroptosis and the Nissl body in PAP-regulated CUMS-exposed depression." (PMID 35401226, 2022). "The result indicated that SIRT1 regulated depression-like behavior by regulating the BDNF expression, and SIRT1 controlled the S-ketamine-evoked release of BDNF in the mPFC of mice, providing a new explanatory mechanism for S-ketamine antidepressant." (PMID 35664490, 2022). "Taken together, these results reveal that lncRNA-84277 serves as a sponge for miR-128-3p to regulate SIRT1 expression and improves SNI-induced depression-like behaviors via a ceRNA mechanism." (PMID 35959106, 2022). "Therefore, the SIRT1 gene may change the microstructure of the subfrontal tract by regulating the immune-inflammatory mechanism, thereby affecting visual, emotional, and executive functions of patients with depression." (PMID 36177213, 2022). "Sirt1, a NAD+-dependent deacetylase, plays a key role in NAD salvage pathway II and mediates the levels of anxiety and depression." (PMID 35130906, 2022). "Kim’s study showed that the SIRT1 inhibitor, EX527, protects stressed mice from depression and anxiety, but, in contrast, EX527 treatment via bilateral injection into the hippocampus led to depressive-like behaviours in chronic ultra-mild-stress-induced mice." (PMID 33669121, 2021). "This review will discuss the evidence to date in relation to the purported role of SIRT1 and SIRT2 modulators in the treatment of depression." (PMID 33669121, 2021). "Two important members, SIRT1 and SIRT2, have been found to participate in the pathophysiology of depression." (PMID 33669121, 2021).